HDAC2 (histone deacetylase 2)
Diseases named in the same sentence as HDAC2 in open-access papers (continued):
Sharing a sentence is not in itself a finding about the gene and the disease.
renal cell carcinoma (2 papers, 2008 to 2022). "In renal cell carcinomas moderate to strong nuclear HDAC1, HDAC2 and HDAC3 immunoreactivity was detected in 55.7%, 56.6% and 13.2% of cases, respectively." (PMID 19099586, 2008).
renal fibrosis (2 papers, 2021 to 2023). A final common manifestation of a wide variety of chronic kidney diseases characterized by glomerulosclerosis and tubulointerstitial fibrosis. "HDAC2-/- mice receiving 28 min of warm ischemia had reduced renal fibrosis at 28 days (mean ± SEM of 3.3 ± 0.4% in HDAC2-/- vs. 6.6 ± 7.1% in WT, p = 0.003)." (PMID 33907245, 2021). "PAX8/HDAC2-/- mice also had reduced renal fibrosis at 28 days." (PMID 33907245, 2021).
retinal degeneration (2 papers, 2014 to 2020). Degeneration of the retina. "When these flies were crossed with a line in which Rpd3, the HDAC1 and HDAC2 drosophila ortholog, is inactivated by the expression of an RNAi specific construct, a reduction in retinal degeneration can be clearly observed." (PMID 32409664, 2020). "Previous work demonstrated that HDAC2 comprised approximately 35% of the total HDAC activity in the mouse retina and that retinas lacking HDAC2 underwent less retinal degeneration following ischemic insult." (PMID 25261965, 2014).
rhabdoid tumor (2 papers, 2013 to 2014). An aggressive malignant embryonal neoplasm usually occurring during childhood. "HDAC1 and HDAC2 are overexpressed in primary rhabdoid tumors and rhabdoid tumor cell lines." (PMID 23764045, 2013). "Comparing protein expression in different SMARCB1 negative rhabdoid tumor cell lines (A204, G401, BT16, BT12) with ESCs (OG2; as a control with known highly expressed HDAC1 and HDAC2) demonstrate that group 1 HDAC levels are similarly expressed in rhabdoid tumors and ESC." (PMID 23764045, 2013). "Similarly, the pan-HDAC inhibitor vorinostat (SAHA), which is currently being used against Rhabdoid tumors in clinical trials, would be expected to robustly induce BRM expression; however, since this compound also inhibits HDAC2, it would also result in BRM acetylation and inactivation." (PMID 24913006, 2014).
rhabdomyosarcoma (2 papers, 2019 to 2025). A rare aggressive malignant mesenchymal neoplasm arising from skeletal muscle. "Motif analysis of HDAC2 revealed binding to myogenic E-box in rhabdomyosarcoma cells, and HDAC2 was found asymmetrically loaded at enhancers of CR TFs." (PMID 31285436, 2019). "We previously reported that the nuclear HDACs (HDAC1, HDAC2 and HDAC3) were co-essential in maintaining CR TF circuits in rhabdomyosarcoma." (PMID 41392987, 2025).
sudden sensorineural hearing loss (2 papers, 2017 to 2022). Sensorineural hearing loss which develops suddenly over a period of hours or a few days. "Here, we investigated the protective effects of aminophylline on HDAC2 expression and glucocorticoid sensitivity in lipopolysaccharide (LPS)-induced sudden sensorineural hearing loss in guinea pigs." (PMID 28578424, 2017).
T-cell lymphomas (2 papers, 2014 to 2021). "Here we report that Cx3cr1-dependent combined ablation of Hdac1 and Hdac2 leads to delayed maturation of T-cell precursors and to development of T-cell lymphomas." (PMID 33849645, 2021). "Furthermore, we report that these mice develop a T-cell neoplasia at about 4–5 months of age, suggesting that a Cx3cr1 expressing subpopulation of immature T-cells gives rise to T-cell lymphomas in the combined absence of Hdac1 and Hdac2." (PMID 33849645, 2021).
type 2 diabetes (2 papers, 2004 to 2016). "In patients with type 2 diabetes, we also observed significantly decreased HDAC2 mRNA expression in PBMCs." (PMID 27904654, 2016). "While the functional significance of alterations in HDAC1 and HDAC2 needs to be clarified in metabolic disorders, our study unraveled a consistent increase in both HDAC3 activity and HDAC3 transcriptional levels in PBMCs from patients with type 2 diabetes." (PMID 27904654, 2016).
adrenocortical carcinoma (1 paper, 2019). "Epigenetically plastic SW13 adrenocortical carcinoma cells were treated with FK228, an HDAC inhibitor with high affinity for HDAC1 and, to a lesser extent, HDAC2." (PMID 30651077, 2019).
age (1 paper, 2019). A temporal measurement of the time period elapsed since an identifiable point in the life cycle of an organism. "Future studies will fully explore the role of CS in accelerating senescence pathways and dissect the precise interactions amongst TLR4, HDAC2, and p16INK4a, which will offer additional molecular targets in treating a range of age‐related lung pathologies." (PMID 30790400, 2019).
alopecia (1 paper, 2013). Hair loss usually from the scalp. "Strikingly, deletion of a single Hdac2 allele in HDAC1 knockout mice results in severe epidermal defects, including alopecia, hyperkeratosis, hyperproliferation and spontaneous tumour formation." (PMID 24240174, 2013).
amyloid (1 paper, 2025). "In line with this, a recent study found that genetic ablation of microglial HDAC1 and HDAC2 in an AD mouse model reduced amyloid plaque burden and rescued memory deficits, suggesting HDAC modulation in microglia as a potential therapeutic target." (PMID 40300607, 2025).
anaplastic oligoastrocytoma (1 paper, 2021). An oligoastrocytoma characterized by the presence of increased cellularity, nuclear atypia, pleomorphism, and high mitotic activity. "The other two studies found that HDAC2 significantly under-expressed in anaplastic oligoastrocytoma (n = 6) with a fold change of 4.40 (p = 5.95E-04), and in GBM (n = 22) with a fold change of 3.68 (p = 2.70E-10)." (PMID 34540896, 2021).
anovulation (1 paper, 2023). The absence of ovulation. "This study demonstrated nuclear translocation of CK2α to phosphorylate HDAC2 is essential for ovulation, which may explain the mechanism of androgen-AR-CK2α axis-induced anovulation in PCOS patients." (PMID 37076890, 2023).
Ataxia (1 paper, 2011). Ataxia refers to impaired coordination of voluntary muscle movement. "Moreover, HDAC2 interacts with ATM and inhibits its function leading to neuronal cell cycle reentry and degeneration in ataxia." (PMID 22582024, 2011).
Azoospermia (1 paper, 2025). Absence of any measurable level of sperm,whereby spermatozoa cannot be observed even after centrifugation of the semen pellet. "Immunofluorescence staining of the testes revealed that the histone methyltransferase EZH2 and Leydig cell marker gene IL6 or HDAC2 were upregulated in azoospermia." (PMID 40756901, 2025). "Moreover, we detected HDAC2 upregulation in azoospermic testes compared to that in normal controls, which further indicates its importance in azoospermia." (PMID 40756901, 2025).
brain cancer (1 paper, 2024). A primary or metastatic malignant neoplasm affecting the brain. "HDAC2 activity regulates chromatin compaction that impacts the expression of SMAD3 and SOX2 and is, thus, critical for the self-renewal of brain cancer cells." (PMID 39063083, 2024).
brain malformations (1 paper, 2017). "Although these results suggested that either HDAC2 or MARCKS alone might not cause brain malformations, haploinsufficiency of both genes may be relevant to MICPCH due to the collapse of the interaction between them." (PMID 28783747, 2017).
breast invasive ductal carcinoma (1 paper, 2020). "Immunohistochemical staining of HDAC1, HDAC2, and HDAC3 in 161 samples from breast invasive ductal carcinoma patients, including 63 patients with brain metastasis, was performed using the standard streptavidin‐peroxidase method." (PMID 32686908, 2020).
carcinoid (1 paper, 2015). "However, expression of HDAC1 and HDAC2 were uncoupled in neuroendocrine cell lines, so that in each case one of the isoenzyme transcripts was markedly elevated relative to the other: HDAC2 in SCLC (NCI-H69, NCI-H345 and Lu-165) and HDAC1 in the NCI-H727 carcinoid cell line." (PMID 25970771, 2015).
carcinoma in situ (1 paper, 2014). "Strong staining of HDAC-1 and HDAC-2 was associated with higher grading (both WHO 1973 and 2004), additionally tumours with high expression levels of HDAC-2 presented more often with adjacent carcinoma in situ compared to tumours with weak HDAC-2 staining." (PMID 24624923, 2014).
Cerebral atrophy (1 paper, 2018). Atrophy (wasting, decrease in size of cells or tissue) affecting the cerebrum. "Conversely, TOPK siRNA down-regulated M2 marker, aggravated cerebral atrophy, as well as the sensorimotor functions, which was completely reversed by the selective HDAC1/HDAC2 specific inhibitor FK228." (PMID 29896413, 2018).
chondrosarcoma (1 paper, 2020). A malignant cartilaginous matrix-producing mesenchymal neoplasm arising from the bone and soft tissue. "Of note, the expression of HDAC2, HDAC7, and HDAC10 seemed to be increased in chondrosarcoma cell lines as compared to healthy human cartilage, and romidepsin targets one of these subtypes (i.e., HDAC2)." (PMID 33266275, 2020).
chorioamnionitis (1 paper, 2014). A morphologic finding indicating inflammation of the fetal sac membranes. "Further studies are needed to clarify the mechanisms how HDAC2 regulates the TGF-α/EGFR pathway in newborns suffering from maternal chorioamnionitis exposure." (PMID 24595367, 2014).
chromophobe carcinoma (1 paper, 2021). "For example, in RCC (including chromophobe carcinoma, ccRCC, and papillary cell carcinoma), low expression of HDAC1, HDAC2, HDAC3, HDAC8, HDAC10 and high expression of HDAC5, HDAC7, HDAC11 have longer survival time." (PMID 34308568, 2021).
chronic lung disease (1 paper, 2022). According to the definitions of the American and British Thoracic Societies, including pulmonary functional tests, X-rays, and CT scans for items such as fibrosis, bronchiectasis, bullae, emphysema, nodular or lymphomatous abnormalities. "Theophylline is also a potent activator of HDAC2, and low doses are sufficient to activate HDAC2; thus, its therapeutic use as HDAC2 activator would present the advantage of strongly reduced risk of potential adverse events as compared to its use in the treatment of chronic lung diseases." (PMID 35740439, 2022).
colon adenocarcinoma (1 paper, 2025). "First, a negative correlation between HDAC2 and the IFIT family was observed in colon adenocarcinoma and rectum adenocarcinoma at the Chipbase database." (PMID 39928532, 2025).
congestive heart failure (1 paper, 2025). Failure of the heart to pump a sufficient amount of blood to meet the needs of the body tissues, resulting in tissue congestion and edema. "In a murine model of congestive heart failure (CHF), HDAC1 and HDAC2 also contributed to MF by participating in the IL‐6/STAT3 signalling pathway." (PMID 40497340, 2025).
cystic fibrosis (1 paper, 2020). Autosomal recessive disorder caused by pathogenic variants in the CFTR gene (cystic fibrosis transmembrane conductance regulator), which encodes a chloride and bicarbonate channel expressed in epithelial cells, and follow the diagnosis criteria. "Additionally, histone deacetylase 2 (HDAC2) has been reported to inhibit the Nfr2/HO-1 pathway in cystic fibrosis epithelial cells." (PMID 32849503, 2020).
diffuse B large cell lymphoma (1 paper, 2018). "Overexpression of HDAC1, HDAC2, and HDAC6 and of higher acetylation levels of histone H4, with respect to the normal lymphoid tissue, have been reported by immunohistochemical studies conducted in patients with peripheral T-cell lymphoma (PTCL), and diffuse B large cell lymphoma (DLBCL)." (PMID 30096875, 2018).
ductal carcinoma in situ (1 paper, 2021). "For instance, in 58 breast samples, acetylated histone H4, H4K12ac, acetylated tubulin, HDAC1, HDAC2, and HDAC6 were lower in ductal carcinoma in situ (DCIS) and invasive ductal carcinoma (IDC) than in normal mammary epithelium." (PMID 34595180, 2021).
E. coli infection (1 paper, 2025). "In addition, knockout or inhibition of HDAC2 significantly reduced the NETs formation, and impaired the antimicrobial activities against E. coli infection in mice." (PMID 40850685, 2025).
esophageal adenocarcinoma (1 paper, 2024). A malignant tumor with glandular differentiation arising predominantly from Barrett mucosa in the lower third of the esophagus. "HDAC2 overexpression showed a statistically significant correlation with increased lymphatic spreading of the tumor (N stage) and lower tumor differentiation (higher grade) in esophageal adenocarcinomas." (PMID 39063083, 2024).
fibrosarcoma (1 paper, 2013). A malignant mesenchymal fibroblastic neoplasm affecting the soft tissue and bone. "In corroboration with previous studies in primary cells, deletion of Hdac1 alone or knockdown of Hdac2 alone in fibrosarcoma cells did not result in any increase in H4K5ac." (PMID 23947532, 2013).
Gaucher disease (1 paper, 2020). Gaucher disease (GD) is a lysosomal storage disorder encompassing three main forms (types 1, 2 and 3), a fetal form and a variant with cardiac involvement (Gaucher disease - ophthalmoplegia - cardiovascular calcification or Gaucher-like disease). "Interestingly, emerging oncology and non-oncology drugs such as the HDAC inhibitors and miglustat, an approved drug for Gaucher’s disease, were amongst potential drug repurposing candidates that target fitness genes in tractability group 1 (targeting HDAC2 and UGCG respectively)." (PMID 32990596, 2020).
gestational diabetes mellitus (1 paper, 2021). "HDAC2 is down‐regulated in the peripheral blood monocytes/macrophages from patients with gestational diabetes mellitus, which is characterized by high serum levels of pro‐inflammatory cytokines, and HDAC2 inhibition aggravates the secretion of pro‐inflammatory cytokines in the monocytes/macrophages." (PMID 34145738, 2021).
glomerular diseases (1 paper, 2023). "VPA can specifically inhibit HDAC1 and HDAC2, and previous studies have demonstrated that VPA treatment improves AKI, glomerular diseases, and UUO in mice." (PMID 37153759, 2023).
glucocorticoid resistance (1 paper, 2020). "However, since HDAC2 activation was not investigated in this study, future research may focus on the involvement of HDAC2 in AGE-induced glucocorticoid resistance." (PMID 32050634, 2020).
gouty arthritis (1 paper, 2019). "Here, we identify the simultaneous inhibition of HDAC1 and HDAC2 as a possible new treatment option in acute gouty arthritis." (PMID 30728075, 2019).
hearing loss (1 paper, 2023). "In an animal acute LPS-induced hearing loss model, the histone deacetylase 2 Hdac2/transcription factor Sp1/miR-204-5p/apoptosis suppressor gene Bcl-2 regulatory axis mediated apoptosis in the cochlea." (PMID 37181652, 2023).
hepatoblastoma (1 paper, 2011). Hepatoblastoma (HB) is a malignant hepatic tumor and is the most common pediatric liver cancer. "High level of HDAC2 expression was detected in all tested cell lines, while β-catenin was not detectable in HepG2, a hepatoblastoma cell line or c-Myc expression varied in different liver cell lines." (PMID 22132221, 2011).
Hyperchloremia (1 paper, 2020). An abnormally increased chloride concentration in the blood. "The whole-nephron HDAC1/HDAC2-deficient animals had the most severe imbalances, presenting with significant hypernatremia/hyperchloremia and death within 30 days of knockdown." (PMID 32673289, 2020).
hyperlipidaemia (1 paper, 2019). "In addition, EHM inhibited hyperlipidaemia by restoring the expression of genes and proteins related to DNA repair and energy metabolism, and proteins such as Hdac2, Xrcc2, Xrcc3, Uhrf1, and Prkar2b were identified as molecular targets playing key roles in ameliorating hyperlipidaemia." (PMID 31545933, 2019).
Infertility (1 paper, 2013). "The infertility of mice harboring Hdac1−/+/Hdac2−/−oocytes is attributed to failure of those few eggs that properly mature to metaphase II to initiate DNA replication following fertilization." (PMID 23516383, 2013). "In summary, the results reported here provide further evidence for a critical role of HDAC2 in oocyte development and provide explanations for the infertility observed in Hdac1−/+/Hdac2−/− and sub-fertility in Hdac2−/− female mice." (PMID 23516383, 2013). "We report here a characterization of the infertility and sub-fertilty phenotypes observed in mice harboring Hdac1−/+/Hdac2−/− or Hdac2−/− oocytes, respectively." (PMID 23516383, 2013). "The molecular basis for the sub-fertility of mice harboring Hdac2−/− oocytes or infertility of mice harboring Hdac1−/+/Hdac2−/−, however, was not examined." (PMID 23516383, 2013). "The incidence of aneuploidy in Hdac2−/− eggs could account for the observed sub-fertility in mutant female mice, but would not account for the infertility in Hdac1−/+/Hdac2−/− mice." (PMID 23516383, 2013).
injury (1 paper, 2019). Damage inflicted on the body as the direct or indirect result of an external force, with or without disruption of structural continuity. "By introducing HDAC2-specific shRNA into the spinal cord via a lentivirus vector, we confirmed that HDAC2 mediates mechanical and thermal hyperalgesia after nerve injury." (PMID 31024248, 2019).
intestinal tumour (1 paper, 2021). "As expected, we found that mouse Ppp2r1a−/− intestinal tumour samples showed higher levels of phospho-Rb and phospho-HDAC2 than the control." (PMID 34911954, 2021).
invasive carcinoma (1 paper, 2008). A carcinoma that is not confined to the epithelium, and has spread to the surrounding stroma. "Lesions of high-grade PIN in the vicinity of invasive carcinomas were identified in 56 (HDAC1), 57 (HDAC2) and 67 (HDAC3) cases, respectively." (PMID 18212746, 2008). "Expression of HDACs in high-grade PIN was almost identical with the strength of expression in the corresponding invasive carcinomas (HDAC1: r=0.961, P<0.001, HDAC2: r=0.756, P<0.001, HDAC3: r=0.694, P<0.001), indicating that HDAC overexpression is an early event in prostate carcinogenesis." (PMID 18212746, 2008).
laminopathies (1 paper, 2018). "Nevertheless, impaired HDAC2 recruitment to the lamin A/C‐containing platform occurs irrespective of the mutated LMNA sequence, a finding that suggests involvement of other molecular defects common to progeroid laminopathies, such as prelamin A accumulation." (PMID 30109767, 2018).
latent infection (1 paper, 2024). "In this model, the transcriptional repressor HDAC2 is synergistically upregulated by HIV and nicotine, leading to more compact chromatin organization, reduced gene transcription, and increased latent infection." (PMID 39529883, 2024).
learning disorders (1 paper, 2018). "It is known that abnormal acetylation takes place in memory and learning disorders such as AD, where significant increase of histone deacetylase 2 (HDAC2) inhibits gene expression of specific locus, such as autophagy markers." (PMID 29675133, 2018).
lentivirus infection (1 paper, 2017). Virus diseases caused by the Lentivirus genus. "To validate the effect of HDAC2 on cell viability of HCT116 cells, we used lentivirus infection to realize HDAC2 knockdown." (PMID 28538837, 2017).
leprosy (1 paper, 2019). Leprosy is a chronic infectious disease affecting primarily the skin and peripheral nervous system. "Additionally, we observed that a classification of leprosy patients is possible using transcriptomics since a set of genes were increased in BL/LL patients (CD46, CXCL10, FCGR1A, HDAC2 and TLR4) and TT/BT showed a higher expression of IL2 and TLR6." (PMID 31784594, 2019).
liver fibrosis (1 paper, 2018). "Pirfenidone, but also LBH589, reduced significantly the protein expression of HDAC1, HDAC2, and of a ~66 kDa isoform of class-IIa-HDAC9, a HDAC comprising several alternatively spliced isoforms with profibrotic function in liver fibrosis." (PMID 30481203, 2018).
liver steatosis (1 paper, 2022). "Sodium butyrate improved liver steatosis by upregulating GLP-1R expression and p-AMPK/p-ACC, by inhibiting HDAC2." (PMID 36077368, 2022).